TARID (TCF21 antisense RNA inducing promoter demethylation)
Synonyms: EYA4-AS1
Gene: Long non-coding RNA gene on chromosome 6 (133,485,013 to 133,953,083, reverse strand). Ensembl gene ENSG00000227954.
Diseases named in the same sentence as TARID in open-access papers:
TARID is named in the same sentence as 12 diseases in open-access papers, as found by Europe PMC text mining. Sharing a sentence is not in itself a finding about the gene and the disease. The quoted sentences say what the papers report.
coronary artery disease (1 paper, 2019). "Variants within TARID or its target (ie TCF21) are associated with coronary artery disease, blood pressure, cis-effects on circulating cytokines, and visceral fat." (PMID 31622379, 2019).
head and neck squamous cell carcinoma (1 paper, 2017). A squamous cell carcinoma that arises from any of the following anatomic sites: lip and oral cavity, nasal cavity, paranasal sinuses, pharynx, larynx, and salivary glands. "TARID and TCF21 are silent and heavily covered by DNA methylation in non-small cell lung cancer (NSCLC), head and neck squamous cell carcinomas (HNSCC) and ovarian cancers (OVC)." (PMID 28747406, 2017).
lung carcinoma (1 paper, 2016). "For lung cancer, various lung cancer-specific lncRNAs have been identified, such as MALAT1, TARID, and LUADT1." (PMID 27154193, 2016).
Wilms tumor (1 paper, 2015). An embryonal neoplasm characterized by the presence of epithelial, mesenchymal, and blastema components. "We show that CCSKs have a significantly lower TARID expression compared to Wilms tumors, negatively correlating with the level of TCF21 promoter methylation." (PMID 26158413, 2015). "Expression of both TARID (NR_109982) and the TARID isoforms KF484511 and KF484512 (isoforms reported to have the strongest demethylation activity) was much lower in CCSKs than in Wilms tumors; in most CCSKs TARID was undetectable." (PMID 26158413, 2015).
tumor (5 papers, 2015 to 2024). "TCF21 is a tumor-suppressor gene regulating the cell cycle, and the TARID-regulated mechanism allows TCF21 expression in normal cells while both TARID and TCF21 are hypermethylated, and hence downregulated, in cancer cells." (PMID 38203767, 2024). "TCF21 hypermethylation and decreased TARID expression were validated in an independent set of CCSK tumor samples." (PMID 26158413, 2015). "Since the inactivation of tumor suppressor genes occurs frequently in cancer cells, it can be inferred that TARID, GADD45 and the associated proteins are part of a surveillance mechanism that protects the promoter of tumor suppressor genes from epigenetic silencing via hyper methylation." (PMID 29443889, 2018). "A previous study has shown that TARID activated TCF21 expression by interacting with both the TCF21 promoter and GADD45A during tumor development." (PMID 36401313, 2022).
TARID also shares sentences with these, for which no sentence is quoted: cancer (1 paper); glioma (1); lymphoma (1); non-small cell lung carcinoma (1); ovarian carcinoma (1); preeclampsia (1); renal clear cell sarcoma (1).